HGF (hepatocyte growth factor)
Diseases named in the same sentence as HGF in open-access papers (continued):
Sharing a sentence is not in itself a finding about the gene and the disease.
injury (14 papers, 2016 to 2026). Damage inflicted on the body as the direct or indirect result of an external force, with or without disruption of structural continuity. "After acute liver injury, KCs produce anti-inflammatory mediators like IL-1 receptor antagonist (IL-1Ra) as well as hepatocyte growth factor (HGF) and vascular endothelial growth factor (VGEF) for tissue remodeling." (PMID 41528365, 2026). "Following acute liver injury, they secrete growth factors, such as hepatocyte growth factor (HGF), which stimulate hepatocyte proliferation and drive the restoration of liver mass and function." (PMID 41293237, 2025). "In the present study, in mice with carbon tetrachloride (CCl4)-induced acute or chronic liver injury, we detected significant upregulation of HGF in the serum and liver." (PMID 39000343, 2024). "In vivo and in vitro studies indicate that HGF promotes alveolar epithelial and endothelial repair after acute lung injury via induction of counterinflammatory and antioxidant gene expression." (PMID 34111030, 2021). "Here, we used a rat model of ischemic-reperfusion nerve injury (IRI) to investigate possible effects of hepatocyte growth factor (HGF) against ischemic neuropathy." (PMID 32780756, 2020). "Recent studies have shown HGF to play a role in acute liver injury, by protecting against isoniazid- and rifampicin-oxidative liver damage." (PMID 29085386, 2017). "Therefore, the HGF/c-met pathway activated by nerve injury might induce some factor(s) in situ that is used to send a signal to the cell body." (PMID 33718632, 2021). "In addition, HGF, with its antifibrotic effect, has been applied in many lung injury diseases." (PMID 33747095, 2021). "We have investigated whether nonviral retrograde gene transfer of HGF might improve ischemic neuropathy using the rat model of ischemic-reperfusion nerve injury (IRI)." (PMID 32780756, 2020). "Besides, hepatocyte growth factor (HGF) derived from MSC-MVs has been shown to reduce pulmonary microvascular endothelial paracellular and transcellular permeability by facilitating the expression of junction proteins VE-cadherin and occluding under pathological conditions such as acute lung injury." (PMID 34020704, 2021). "As the direct mechanism of HGF and PGE2 production by SkMSCs has not been validated in a model of acute alcohol-induced liver injury, our study had limitations." (PMID 35165521, 2022).
ischemic heart disease (14 papers, 2010 to 2025). "In other studies, HGF has been reported as a marker of arteriosclerosis, peripheral arterial occlusive disease and incident coronary heart disease; also, it has been associated with poor prognosis in acute coronary syndromes." (PMID 35482134, 2022). "Another study from the same cohort found that every standard deviation increase in circulating HGF was associated with 12% greater odds of having any coronary artery calcium and 20% increased risk of coronary heart disease after adjusting for traditional CVD risk factors." (PMID 35047572, 2021). "Based on these studies, small, open-label clinical studies on HGF for ischemic heart disease were performed." (PMID 36826582, 2023). "In patients with ischemic heart disease, the prognosis value of serum levels of HGF has demonstrated contradictory results." (PMID 35482134, 2022). "HGF gene therapy has also been used in the treatment of ischemic heart disease and for tissue regeneration." (PMID 33439866, 2021). "As a part of it, in the present study, we intended to examine a combinatory cell therapy using BM-MSCs and HGF-eMSCs, which we named in situ preconditioning strategy, to promote the therapeutic efficacy of hMSCs for the treatment of ischemic heart disease." (PMID 33535594, 2021). "HGF has been used successfully as both protein and DNA as a therapeutic agent in preclinical animal models for ischemic heart disease, renal fibrosis, pulmonary fibrosis, and for other diseases where there is a need for increased tissues repair." (PMID 28548073, 2014). "The phase I clinical study showed that it is safe and effective to use an adenoviral gene-transfer vector to deliver the human HGF to individuals with clinically significant coronary artery disease." (PMID 23301013, 2013). "Hepatocyte growth factor (HGF) is one of the major angiogenic factors being studied for the treatment of ischemic heart diseases." (PMID 23301013, 2013). "Our phase I clinical study showed that it was safe and effective using an adenoviral gene transfer vector to deliver the human HGF to individuals with clinically significant coronary artery disease." (PMID 23301013, 2013). "Because of its potential angiogenic, anti-apoptotic, anti-fibrotic and anti-inflammatory benefits, HGF has received increasing attention in ischemic heart disease." (PMID 23554631, 2010). "The most studied factors as pertains to coronary disease are vascular endothelial growth factor (VEGF), placental growth factor (PlGF) and hepatocyte growth factor (HGF)." (PMID 22708908, 2012). "In patients with AS with and without ATTR-CM, levels of decorin and HGF correlated positively with age and the presence of coronary artery disease." (PMID 41141478, 2025). "Furthermore, plasmid expression of HGF is in Phase III Clinical Trials to treat severe peripheral arterial disease in Japan, and adenovirus mediated HGF gene-transfer is under investigation as a potential treatment for coronary artery disease in a Phase I Clinical Trial in China." (PMID 28548073, 2014).
acute liver failure (13 papers, 2013 to 2025). Rapid deterioration of liver function causing encephalopathy and coagulopathy. "The clinical trial NCT03017016 evaluates the safety and efficacy of the HGF gene therapy drug HGF-ung1 specifically in patients with acute liver failure." (PMID 40304568, 2025). "The trial NCT02083768 focuses on the safety and initial efficacy of HGF gene therapy in patients diagnosed with acute liver failure." (PMID 40304568, 2025). "Recombinant human HGF (rh-HGF) can significantly inhibit hepatocyte death and stabilize structural and vascular integrity in mice with acute liver failure (ALF)." (PMID 35370682, 2022). "Serum APOA4 levels were increased after rh-HGF administration, not only in normal mice but also in anti-Fas-induced murine acute liver failure (ALF), which confirmed the pharmacodynamic nature of APOA4." (PMID 33925510, 2021). "The beneficial effect of HLSCs in the lethal model of acute liver failure depended, at least in part, on HGF production." (PMID 31281379, 2019). "In this study, we biochemically and histologically characterized the effects of rh-HGF on in vitro human hepatocyte injury and mouse acute liver failure (ALF) models, both of which were induced by antibody-mediated Fas signaling." (PMID 31013780, 2019). "In this study, we investigated the therapeutic potential of UCMSCs that overexpress hepatocyte growth factor (HGF) in an acetaminophen-induced acute liver failure mouse model." (PMID 27057357, 2016). "Taken together, these data suggest that ectopic expression of HGF in UCMSCs protects animals from acetaminophen-induced acute liver failure through antiapoptosis and antioxidation mechanisms." (PMID 27057357, 2016). "We found that the HGF-UCMSC cell therapy protected animals from acute liver failure by reducing liver damage and prolonging animal survival." (PMID 27057357, 2016). "We demonstrate that systemically administered HGF-UCMSCs protect animals with acute liver failure by alleviating hepatic injuries and prolonging the survival." (PMID 27057357, 2016). "Recently, a clinical trial using recombinant HGF for acute liver failure has been reported, and it has been shown that intravenous administration of recombinant HGF is well-tolerated." (PMID 24141186, 2013). "In addition, overexpressing hepatocyte growth factor (HGF) modulated apoptosis of UC-MSCs and protected animals from acute liver failure." (PMID 34977045, 2021). "Since its discovery, vigorous research has been conducted on HGF world-wide, which revealed its pleiotropic activities, among which its strong and rapid anti-apoptotic effects against murine liver injury led to the dynamic investigation into a fatal and disastrous condition, acute liver failure." (PMID 33925510, 2021). "In patients with acute liver failure (ALF), levels for HGF, ICAM-1, and IFN-α2 were found to be elevated compared to patients with biliary atresia or liver tumor patients." (PMID 30740106, 2019). "In contrast, levels of HGF, LIF, M-SCF, VCAM, and ICAM1 were highest for acute liver failure (ALF) and lowest for tumor patients, indicating that tissue damage plays the largest pathophysiological role in patients with ALF." (PMID 30740106, 2019).
breast tumor (13 papers, 2010 to 2026). "In the context of breast tumors, clinical studies have identified a correlation between HGF pathway activation (as determined by c-MET overexpression) and increased tumor size, high tumor grade, and distant metastasis." (PMID 41597220, 2026). "The HGF/c-MET signaling pathway then modulates the breast tumor microenvironment and drives malignant transformation by inducing c-MET dimerization and phosphorylation, which activates downstream pathways such as MAPK and PI3K21." (PMID 40665092, 2025). "In breast tumors, clinical studies have correlated activation of the HGF pathway (as defined by c-MET over-expression) with increased tumor size, high tumor grade, and distant metastasis." (PMID 34344422, 2021). "Treatment of human and mouse breast tumor cells with the CD44v6-binding peptides inhibited the HGF-induced phosphorylation of c-Met and downstream signaling factors such as Erk and subsequently inhibited cell migration and invasion." (PMID 33391537, 2021). "Invasive breast tumors from 1957 patients were assessed for a 38-gene RNA-based HGF gene expression signature." (PMID 34344422, 2021). "In contrast, several groups have suggested that HGF is expressed in the breast tumor cells via mRNA detection using in situ hybridization." (PMID 20624308, 2010). "This shift between HGF-induced c-Met activation and inhibition of c-Met signalling by BFE, could be a pivotal step controlling the metastatic influence of HGF, thus limiting breast tumour progression." (PMID 30314527, 2018). "Analysis of 965 primary breast tumors from TCGA RNA‐seq dataset showed that breast tumors harboring H1047R and other PIK3CA mutations (including E545K and E542K) have significant upregulation of AXIN2, HGF, STAT3, IGF‐1, and IGF‐2 mRNA compared with PIK3CA‐wild‐type and HER‐2‐amplified tumors." (PMID 28296140, 2017). "Moreover, HGF may promote the invasiveness and metastasis of breast tumor xenografts in BALB/c-nu mice via the PKCζ-mediated pathway, while suppression of PKCζ by RNA interference may abrogate cancer cell spreading." (PMID 22242160, 2012).
cholangiocarcinoma (13 papers, 2015 to 2025). A carcinoma that arises from the intrahepatic biliary tree (intrahepatic cholangiocarcinoma) or from the junction, or adjacent to the junction, of the right and left hepatic ducts (hilar cholangiocarcinoma). "Ongoing study of these pathways as well as others found to be implicated in cholangiocarcinoma including map kinase pathway, hepatocyte growth factor, BRAF, and platelet derived growth factor hopefully will lead to effective targeted therapy." (PMID 26089873, 2015). "HRH2 and HGF were primarily expressed in CAFs within the tumor microenvironment of cholangiocarcinoma." (PMID 41048570, 2025). "That HGF promotes the progression of cholangiocarcinoma was identified by using orthotopic models and in vitro experiments." (PMID 41048570, 2025). "HGF upregulates the phosphorylation of FOS-like 1 (FOSL1) within cholangiocarcinoma cells, promoting the expression of matrix metallopeptidase 10 (MMP10), and consequently enhancing the invasive and migratory abilities of cholangiocarcinoma cells." (PMID 41048570, 2025). "FAK activation mediated HGF-induced proliferation and invasion of the human cholangiocarcinoma cell line, HuCCA-1." (PMID 35625759, 2022). "Other mediators upregulated in cholangiocarcinoma include Transforming Growth Factor-β, Vascular Endothelial Growth Factor, Hepatocyte Growth Factor and several microRNAs." (PMID 30819129, 2019). "Additionally, in cholangiocarcinoma, iCAF has been shown to enhance tumour growth by expressing HGF, which can directly interact with the tumour‐expressed MET receptor." (PMID 38445456, 2024). "However, this receptor is anomalously high in cholangiocarcinoma along with its ligand hepatocyte growth factor (HGF) leading to enhance cell proliferation, angiogenesis, and metastasis." (PMID 33507701, 2021). "Additionally, treatment of HGF-stimulated cholangiocarcinoma cells with MET siRNA led to the disappearance of actin-rich protrusions." (PMID 31649529, 2019). "Other targets, such as anti-angiogenesis, EGFR amp, WNT/a-catenin, Hedgehog, and HGF/c-MET, have been reported in cholangiocarcinoma, but most of these pathways can be found in most tumour types, and multiple previous clinical trials in cholangiocarcinoma have shown limited effectiveness." (PMID 36612035, 2022). "EGF, HGF/MET, VEGF, KRAS/MAPK, and IL-6/STAT pathways have been found to be deregulated in cholangiocarcinoma, but no effective therapies targeting these pathways have been developed." (PMID 26475437, 2015).
colitis (13 papers, 2014 to 2025). Inflammation of the colon. "In contrast, it has been found that fetal swallowing of amniotic fluid containing HGF decreases NEC incidence in rats and that induced colitis yields greater damage in HGF-deficient mice." (PMID 34746064, 2021). "In this study, we examined the therapeutic effect of injecting an adenoviral vector encoding the human HGF gene (Ad.HGF) into the hindlimbs of mice with dextran sodium sulfate (DSS)-induced colitis." (PMID 24604303, 2014). "With regard to the therapeutic mechanism, previous studies have reported that administration of recombinant HGF protein and vector encoding HGF gene ameliorate TNBS-induced colitis and reduced inflammation, decreasing the levels of inflammatory cytokines such as TNF-α." (PMID 24604303, 2014). "Paradoxically, NF-κB signaling in CAFs has dual regulatory roles: IKKβ activation suppresses hepatocyte growth factor (HGF)-mediated intestinal tumorigenesis via SMAD7 and SMURF1 induction but promotes colitis-associated cancer through IL-6 overproduction." (PMID 40562870, 2025). "On the other hand, HGF is dramatically upregulated in the serum and intestinal mucosa of patients with colitis." (PMID 40427685, 2025). "In this study, we assessed the effect of a diet rich in leucine on DSS-induced colitis in hGF-SAMP mice." (PMID 39519299, 2024). "In conclusion, this study gives important insights into the various effects of leucine-rich diets on DSS-induced colitis in hGF-SAMP mice." (PMID 39519299, 2024). "Reducing the expression of c-Met (the receptor of HGF) in colitis neutrophils alleviates the severity of colitis, indicating that HGF may be involved in gut damage." (PMID 40427685, 2025). "Thus, the IFN-γ-induced lineage replacement from BMP-high to BMP-low colonocytes during colitis triggers the expression of HGF in stromal cells." (PMID 40319019, 2025). "Mice deficient in HGF-activator showed no abnormal tissue homeostasis, but the injured mucosa was not sufficiently covered by regenerated epithelium following colitis-induced injury." (PMID 31212972, 2019). "The systemic administration of recombinant human HGF protein ameliorated experimental colitis." (PMID 25933295, 2015). "This study evaluated the therapeutic potential of the intramuscular injection of HGF-expressing Ad for treating IBD, using a mouse model of DSS-induced colitis." (PMID 24604303, 2014). "In addition, administration of recombinant human HGF (hHGF) protein reduces the severity of colitis and accelerates colonic mucosal repair in models of TNBS-induced and DSS-induced colitis, as well as in HLA-B27 transgenic rats with colitis." (PMID 24604303, 2014). "Endogenous regeneration-promoting factors like HGF were actually up-regulated in response to injury in IBD patients as well as mouse DSS colitis, although this alone may not be enough to recover the damaged tissue in case of chronic ulcers with certain inflammatory conditions." (PMID 27410685, 2016).
leukemia (13 papers, 2014 to 2024). A malignant (clonal) hematologic disorder, involving hematopoietic stem cells and characterized by the presence of primitive or atypical myeloid or lymphoid cells in the bone marrow and the blood. "Cumulative studies also disclosed high expression of c-MET and HGF in different types of lymphoma and leukemia and their microenvironment, respectively; or both in the tumor cells." (PMID 34539876, 2021). "The human stromal cell line HS-5 expresses abundant FGF2, in addition to other soluble cytokines such as IL-5, IL-8 and HGF, and conditioned media (CM) from HS-5 is highly protective of leukemia cell lines." (PMID 30720426, 2019). "Again, the leukaemia-free survival rate of patients with low HGF levels was better than that of AML patients with high HGF levels." (PMID 25119536, 2014). "Interestingly, HGF seems also to be one of the most differentially expressed genes in the leukemia-initiating cells of AML, as compared to normal hematopoietic stem cells." (PMID 30642077, 2019). "Moreover, we will summarize and explore therapies aimed to block survival advantages provided by c-MET/HGF interactions in leukemia." (PMID 30642077, 2019). "Compared to the healthy bone marrow landscape, leukemia cytokine signatures show an increase in transforming growth factor β (TGF-β) and hepatocyte growth factor (HGF) levels." (PMID 35401520, 2022). "M-MΦs secrete prosurvival factors, such as HGF, and EGF, and high levels of VCAM-1, which has been demonstrated to play an essential role in the BM stromal compartment in mediating leukemia cell chemoresistance." (PMID 34771453, 2021). "Serum levels of HGF were higher in AML patients compared to healthy subjects, and HGF was prognostic for complete remission attainment, leukemia-free and overall survival in AML." (PMID 34727888, 2021). "After GO analysis of the seventy-four genes, six secreted cytokines related to cell cycle, proliferation and apoptosis including CSF2, CTF1, FGF2, IGF2, HGF and LIF were selected for PCR verification and FGF2 was confirmed to be significantly up-regulated in leukaemia mice derived MSCs." (PMID 36333298, 2022). "In addition, HGF can induce VEGF production and thus play an important role in the pathophysiology of leukemia." (PMID 34777462, 2021).
multiple sclerosis (13 papers, 2012 to 2025). A progressive autoimmune disorder affecting the central nervous system resulting in demyelination. "MSC-produced HGF has been implicated in promoting the development of oligodendrocytes and neurons in a multiple sclerosis model." (PMID 24572070, 2014). "There is large evidence that HGF can mediate neuroinflammation in the context of neurodegenerative autoimmune diseases such as multiple sclerosis (MS), leading to an indirect effect on the immune system." (PMID 34179015, 2021). "For example, in a multiple sclerosis mouse model HGF/SF has been shown to modulate both CD4+ and CD8+ T cell effector responses." (PMID 33198383, 2020). "The implication of HGF in mediating MSC-stimulated beneficial effects has also been demonstrated in experimental models of multiple sclerosis further indicating a critical role for HGF and c-Met in the recovery from injuries." (PMID 29731780, 2018). "HGF has mediated mesenchymal stem cell-induced recovery in multiple sclerosis models." (PMID 28548072, 2014).